TMPRSS6 (transmembrane serine protease 6)
Diseases named in the same sentence as TMPRSS6 in open-access papers (continued):
Sharing a sentence is not in itself a finding about the gene and the disease.
hemochromatosis (13 papers, 2012 to 2025). A disorder of iron metabolism characterized by a triad of HEMOSIDEROSIS; LIVER CIRRHOSIS; and DIABETES MELLITUS. "Taking all 62 × 11 = 682 tests into account using Bonferroni correction, the TMPRSS6 p.Val749Ala variant (rs855791[A]) associates with less risk of hemochromatosis (Ncases = 719, Ncontrols = 497,001; OR = 0.80 [0.72–0.89], P = 6.1 × 10−5)." (PMID 33536631, 2021). "Under certain pathological conditions such as hemochromatosis, beta-thalassemia, and polycythaemia vera, an increase in hepcidin would lower the iron burden of patients and thus would be beneficial to patients, making TMPRSS6 an appealing therapeutic target to treat iron overload disorders." (PMID 36044454, 2022). "This miRNA, known for its role in the regulation of iron homeostasis, was found to exhibit differential regulation in the livers of animal models of juvenile hemochromatosis (Hjv−/− mice) and IRIDA (Tmprss6−/− mice)." (PMID 37566034, 2023). "The SNPs of the transmembrane protease serine 6 gene (TMPRSS6) rs855791, and the hemochromatosis gene (HFE) rs1800562 and rs1799945 are known to be associated with increased serum iron levels in adults." (PMID 35468817, 2022). "The upregulation of hepcidin transcription in response to iron is mediated by a mechanism depending on the interaction of various proteins including the hereditary hemochromatosis protein HFE, and matriptase-2 (TMPRSS6)." (PMID 23433094, 2013). "However, the relationship between TMPRSS6 genotype and the expression of hemochromatosis is still controversial, and no data are available on the effect on iron overload disorders not related to hepcidin dysregulation." (PMID 23144979, 2012).
iron overload (11 papers, 2012 to 2026). "The results of Fisher’s exact test showed that the simultaneous presence of SLC40A1 and TMPRSS6 SNPs was strongly associated with serum ferritin concentration below 200 μg/L in this iron overload cohort (p < 0.00001; α error of 0.01)." (PMID 36295822, 2022). "Although we detected a likely pathogenic CDAN-1 variant in an asymptomatic subject, its potential role in counteracting the TMPRSS6 defect via low-hepcidin induced iron overload is considered rare and unlikely." (PMID 41595494, 2026). "Several studies have been conducted to study the role of matriptase-2, by crossing Tmprss6 knockout mice with several iron overload mouse models, including the generations of Hjv/Tmprss6, Bmp6/Tmprss6, Hfe/Tmprss6, and Tfr2/Tmprss6 double mutant mice." (PMID 24966834, 2014). "Our results suggest that, by both reducing iron and improving RBC function, inhibition of TMPRSS6 by REGN7999 may offer a therapy for iron overload and impaired erythropoiesis in β-thalassemia." (PMID 40548380, 2025). "The present study is the first to characterize concurrent dysregulation of TMPRSS6, NEO1, and sHJV in transfusion-driven iron overload among pediatric leukemia patients." (PMID 40805193, 2025). "The documented elevation of TMPRSS6 and NEO1 concomitant with reduced sHJV strongly suggests their mechanistic involvement in iron overload, exacerbated by therapeutic and transfusional exposures." (PMID 40805193, 2025). "TMPRSS6 p.Ala736Val status influenced hepatic iron deposition in patients negative, but not in those positive for HFE genotypes at risk for iron overload, whereas HFE genotypes at risk influenced hepatic iron accumulation in patients positive for the p.736Val TMPRSS6 variant." (PMID 23144979, 2012).
hereditary hemochromatosis (8 papers, 2012 to 2026). An inherited metabolic disorder characterized by iron accumulation in the tissues. "In CHD patients, the A736V TMPRSS6 polymorphism influenced serum hepcidin levels in individuals positive for mutations in the HFE gene of hereditary hemochromatosis (p < 0.0001)." (PMID 23433094, 2013). "Therefore, the main results of the present manuscript is that TMPRSS6 p.Ala736Val variant influences iron accumulation even in secondary iron overload disorders which are not caused by a deficit in the upregulation of hepcidin in response to iron, such as hereditary hemochromatosis." (PMID 23144979, 2012). "The common missense variant in TMPRSS6 (rs855791[A], MAF = 43.1%) protects against hereditary hemochromatosis (OR = 0.80 [0.72–0.89], P = 6.1 × 10−5) and could thus be a modifying gene in this disease." (PMID 33536631, 2021).
microcytic anemia (8 papers, 2011 to 2026). Anemia in which the red blood cell volume is decreased. "Patients with homozygous TMPRSS6 mutations display microcytic anemia associated with inappropriately high urinary hepcidin." (PMID 33800732, 2021). "Similarly, mice with Tmprss6 mutations display high hepatic hepcidin (Hamp) mRNA content and severe microcytic anemia." (PMID 33800732, 2021). "TMPRSS6-mutant mice were found to have microcytic anemia and elevated hepcidin levels disproportionate to the degree of anemia." (PMID 25805669, 2015). "In 2011, the search for the physiological function of MT2 has become even more interesting by the observation that the administration of erythropoietin (EPO) fails to correct the microcytic anemia present in Tmprss6-mutated mice." (PMID 33800732, 2021). "Patients with TMPRSS6 mutations display microcytic anemia which does not respond to EPO administration." (PMID 29073189, 2017). "Other TMPRSS6 coding variants have been reported in patients with familial iron-refractory iron-deficiency anemia (IRIDA), a rare autosomal-recessive disorder characterized by hypochromic microcytic anemia and impaired iron balance." (PMID 28787443, 2017). "Mice without functional matriptase-2 (both mask mice with truncated Tmprss6 lacking the protease domain and Tmprss6 knockout mice) showed a hypochromic microcytic anemia and an alopecia." (PMID 24966834, 2014).
breast carcinoma (6 papers, 2007 to 2025). "We also showed that several TMPRSS6 (encoding matriptase-2) variants are related to breast cancer prognosis and matriptase-2 expression levels decrease with tumor progression." (PMID 26014348, 2015). "We also reported a genetic risk factor on TMPRSS6, coding matriptase-2, to be associated with elevated breast cancer risk and poor outcome." (PMID 25029565, 2014). "The association between matriptase-2 and breast cancer was established by a case control study in eastern Finnish population where they found a SNP (rs733655) in TMPRSS6 gene associated with increased breast cancer risk." (PMID 24966834, 2014). "The detection of ~33% of LOH at the TMPRSS6 locus supports its role as a tumor suppressor suggested by a previous observation that TMPRSS6 nucleotide variants conferred a risk of breast cancer." (PMID 17280605, 2007). "Motivated by our previous findings, we hypothesized that in addition to ST14 and TMPRSS6, genes coding TTSPs and related genes exist as variants associated with breast cancer risk and patient outcome." (PMID 25029565, 2014). "Low expression of TMPRSS6 is related to the triple-negative and high grade of breast cancer." (PMID 32793475, 2020). "TMPRSS6 expression is predominantly found in low invasive breast cancer cell lines such as MCF-7 and is absent in more invasive breast cancer cell lines such as MDA-MB-231." (PMID 24966834, 2014).
hepatocellular carcinoma (5 papers, 2013 to 2022). A malignant tumor that arises from hepatocytes. "By analysing RNA-seq data encoding TMPRSS6 isoforms and other proteins involved in hepcidin production, we uncovered significant differences in expression levels between hepatocellular carcinoma (HCC) cell lines and normal human liver samples." (PMID 30135444, 2018). "For this purpose, we selected the commonly used hepatocellular carcinoma cell line Hep3B, known to express TMPRSS6 and several components of the iron regulation pathway as a model system." (PMID 36044454, 2022). "The effect of factors known to regulate TMPRSS6 expression, such as IL‐6, LPS and BMP‐6,39, 42 should be taken into consideration in human hepatoma cell lines, but also in mice to see if they affect expression levels of specific TMPRSS6 isoforms." (PMID 29441715, 2018). "The ability of IL-6 to decrease TMPRSS6 expression was also demonstrated in another human hepatoma-derived cell line, HepG2 cells." (PMID 24376517, 2013). "In this study, we demonstrated that treatment of a hepatoma cell line with IL-6 or injection of IL-6 or LPS in mice decreased TMPRSS6 mRNA expression." (PMID 24376517, 2013). "In the hepatocellular carcinoma cell line Huh7, it was previously demonstrated that TfR1 could be proteolytically cleaved by PC7, encoded by PCSK7, but not by TMPRSS6." (PMID 36044454, 2022).
Obesity (5 papers, 2018 to 2025). Accumulation of substantial excess body fat. "Additional studies will be important to understand how elevated hepcidin levels increase lipolysis in adipose tissue in Tmprss6 KO mice and if matriptase-2 deficiency also protects against obesity in humans." (PMID 37509434, 2023). "Here we demonstrate that the deficiency in the hepcidin repressor matriptase-2 (Tmprss6) protects from high-fat diet-induced obesity." (PMID 29636509, 2018). "We find that matriptase-2 deficiency protects from high-fat diet-induced obesity by increasing fat lipolysis, a phenotype which is dependent on the inadequate hepcidin up-regulation and iron imbalance characteristic of Tmprss6−/− mice." (PMID 29636509, 2018). "More important, hepcidin down-regulation in anti-HJV-treated Tmprss6−/−mice completely abolished the obesity-resistant phenotype observed in matriptase-2 deficient mice on HFD diet." (PMID 29636509, 2018). "In supporting this idea, injection of an anti-hemojuvelin neutralizing antibody in Tmprss6 KO mice reduced hepcidin levels and eliminated the obesity-resistant phenotype." (PMID 37509434, 2023). "Rescue experiments that block hepcidin up-regulation and restore iron levels in Tmprss6−/− mice via anti-hemojuvelin (HJV) therapy, revert the obesity-resistant phenotype of Tmprss6−/− mice." (PMID 29636509, 2018). "In principle, the observed resistance to obesity in high-fat diet-treated Tmprss6 KO mice could be due to high hepcidin levels or low iron levels or both." (PMID 37509434, 2023). "Moreover, a reduction of TMPRSS6 levels has been described as protective against obesity in direct relation with its role in iron homeostasis." (PMID 36044454, 2022). "In controls with missing DNA for TMPRSS6 sequencing (n = 3), the cause of IDA was attributed to gastrointestinal bleeding and obesity, hypermenorrhea and obesity, and medication use (proton pump inhibitor and anticoagulant therapy, good response to oral iron supplementation), respectively." (PMID 35163840, 2022). "However, different in vivo models have shown the promoting role of Id proteins in the development of obesity and fat accumulation, thus ruling out a significant role of these proteins in the obesity-protection observed in Tmprss6−/−mice." (PMID 29636509, 2018). "Moreover, the analysis of lipid levels, frequently altered in obesity, showed a significant reduction in the concentration of plasma cholesterol in Tmprss6−/− mice and in both Tmprss6−/− and Tmprss6+/+ mice treated with iron compared with controls." (PMID 29636509, 2018). "Moreover, down regulation of TMPRSS6 function, which would increase hepcidin plasma levels, could be beneficial in other conditions with unmet medical needs such as infection with siderophilic pathogens, polycythemia vera and obesity." (PMID 36044454, 2022). "When hypoferremia—but not high hepcidin levels—in Tmprss6 mice was corrected via iron injection, the protection against obesity remained." (PMID 37509434, 2023). "Accordingly, the concentration of fasting blood glucose was significantly reduced in both iron-treated Tmprss6−/−and Tmprss6+/+ mice, in which the resistance to diet-induced obesity was more exacerbated, but not in Tmprss6−/−mice compared with wild-type mice." (PMID 29636509, 2018). "Taken together, these data suggest that energy balance might not be the main mechanism responsible for the observed resistance to diet-induced obesity in the absence of matriptase-2, since iron-treated Tmprss6−/−mice behave similar to wild-type mice in this regard but show a marked lean phenotype." (PMID 29636509, 2018).
thalassemia (4 papers, 2021 to 2025). An inherited blood disorder characterized by a decreased synthesis of one of the polypeptide chains that form hemoglobin. "Conversely, LDH activity in erythrocytes is significantly increased in Hbbth3/+ mice, suggesting that RBCs of β-thalassemia mice produce more lactate, especially during exhaustion running; inhibition of TMPRSS6 with REGN7999 improves this." (PMID 40548380, 2025). "Antibody blockade of TMPRSS6 significantly reduces liver iron and improves red blood cell health, resulting in increased physical fitness in a beta-thalassemia mouse model." (PMID 40548380, 2025). "Potential means of improving hepcidin function in thalassemia also include acting on TMPRSS6, TfR1, TfR2 or ferroportin, the target of hepcidin." (PMID 36079046, 2022). "Furthermore, the SiRNA therapy decreases TMPRSS6 expression, thus increasing hepcidin expression and improving the incidence of disease-related thalassemia." (PMID 35052868, 2022). "TMPRSS6 is a negative regulator of hepcidin, and its depletion using small interfering ribonucleic acid siRNA increased hepcidin mRNA and improved erythropoiesis in a β-thalassemia mouse model." (PMID 35052868, 2022). "Besides, and independently of Erfe, hepcidin is regulated by matriptase-2, a transmembrane serine protease encoded by the gene TMPRSS6, whose inactivation by deletion or silencing improves IE in a mouse model of thalassaemia." (PMID 34281283, 2021).
alopecia (3 papers, 2014 to 2024). Hair loss usually from the scalp. "Similar phenotypes and alopecia indicating low iron levels in the body are reported in mouse models with a global Tmprss6 knockout (Tmprss6−/−), a truncated Tmprss6 that lacks the coding sequence for the catalytic domain (mask), or an Ile286Phe substitution in the CUB domain." (PMID 37690687, 2023). "The RBC counts returned to the level of Tmprss6+/+/ICD group, and the alopecia disappeared." (PMID 37690687, 2023).
beta thalassemia (3 papers, 2012 to 2022). Beta-thalassemia (BT) is characterized by deficiency (Beta+) or absence (Beta0) of synthesis of the beta globin chains of hemoglobin (Hb). "The prevalence of beta-thalassemia trait and of HFE genotypes at risk was higher, whereas that of 736V/V TMPRSS6 was lower in patients with hepatic iron (p<0.0001)." (PMID 23144979, 2012). "The TMPRSS6 p.736Val allele was negatively associated with hepatic iron accumulation independently of age, gender, the presence of HFE genotypes at risk, and the beta-thalassemia trait (OR 0.59, 95% confidence interval 0.39–0.88, per each p.736Val allele)." (PMID 23144979, 2012). "However, differently from what was observed in the general population, TMPRSS6 genotype did not influence TS, which on the other hand was modulated by HFE mutations and the beta-thalassemia trait." (PMID 23144979, 2012).
prostate carcinoma (3 papers, 2014 to 2024). A carcinoma that arises from epithelial cells of the prostate gland. "Consistent with the clinical observations, overexpression of Tmprss6 has been found to inhibit the invasion and growth of breast and prostate cancer cells in both in vivo and in vitro experiments." (PMID 38218852, 2024). "Interestingly, Tmprss6 expression has been reported in breast and prostate cancers; however, little is known about the molecular function of Tmprss6 in cancer." (PMID 38218852, 2024). "In addition, aberrant expression of TMPRSS6 is observed in different human cancers such as breast and prostate cancer." (PMID 24966834, 2014).
chronic kidney disease (2 papers, 2019 to 2024). Impairment of the renal function secondary to chronic kidney damage persisting for three or more months. "Influence of TMPRSS6 A736V and HFE (C282Y and H63D) polymorphisms on serum hepcidin-25 levels and iron status parameters in end-stage renal disease (ESRD) patients stratified according to gender has not been previously investigated." (PMID 30984307, 2019).
Fanconi anemia (2 papers, 2016 to 2024). Fanconi anemia (FA) is a hereditary DNA repair disorder characterized by progressive pancytopenia with bone marrow failure, variable congenital malformations and predisposition to develop hematological or solid tumors. "Various causes may contribute to this condition, including genetic defects in proteins responsible for DNA repair, as in Fanconi anemia, and rare genetic mutations occurring in TMPRSS6 (alias matriptase-2) that cause iron refractory iron deficiency anemia (IRIDA)." (PMID 26805813, 2016).
Hepatic steatosis (2 papers, 2018 to 2023). Steatosis is a term used to denote lipid accumulation within hepatocytes. "Consistent with this hypothesis, our data demonstrate that blocking hepcidin up-regulation in Tmprss6−/−mice via anti-HJV therapy, completely reverted hepatic steatosis resistance in matriptase-2 deficient mice." (PMID 29636509, 2018). "Hepdicin down-regulation also resulted in a marked liver steatosis in anti-HJV-treated Tmprss6−/−mice." (PMID 29636509, 2018). "Tmprss6−/− mice show a significant decrease in body fat, improved glucose tolerance and insulin sensitivity, and are protected against hepatic steatosis." (PMID 29636509, 2018).
aceruloplasminemia (1 paper, 2022). An adult-onset disorder of neurodegeneration with brain iron accumulation (NBIA) characterized by anemia, retinal degeneration, diabetes and various neurological symptoms. "Furthermore, several other inherited conditions are associated with alterations in the metabolism of iron and iron overloads, such as iron deficiency–iron refractory anemia (IRIDA, caused by pathogenic variants in TMPRSS6), aceruloplasminemia or hypoceruloplasminemia, and iron-loading anemias." (PMID 36144223, 2022).
angina pectoris (1 paper, 2019). The symptom of paroxysmal pain consequent to MYOCARDIAL ISCHEMIA usually of distinctive character, location and radiation. "The liver iron increasing allele at TMPRSS6 was associated with lower risk of ischaemic heart disease, angina pectoris, and lipidaemias (FDR <5%)." (PMID 31226389, 2019). "The liver iron increasing allele at TMPRSS6 rs855791 was associated with lower LDL-C, lower risk of angina and ischaemic heart disease." (PMID 31226389, 2019).
autism (1 paper, 2024). Persistent deficits in social interaction and communication and interaction as well as a markedly restricted repertoire of activity and interest as well as repetitive patterns of behavior. "We identified 710 SNPs in these lines that indicate new potentially important genes for FP such as TMPRSS6 (implicated in autism), and SST and ARNT2 (somatostatin function)." (PMID 39702044, 2024). "One of these is a G > A substitution in the promoter region of the TMPRSS6 gene, implicated in autism (also a repetitive behaviour) in humans." (PMID 39702044, 2024). "Because autism spectrum disorders in humans involve repetitive behaviour, the finding of this fixed allele in the TMPRSS6 gene of chickens in relation to FP (also a repetitive behaviour) may be of relevance to investigate the etiology of autism." (PMID 39702044, 2024).
COVID-19 (1 paper, 2021). A disease caused by infection with severe acute respiratory syndrome coronavirus 2. "In HNECs treated with HMGB1 and OSM, upregulation of the COVID-19-related genes TMPRSS6, furin, and cathepsin L (CTSL) was observed compared to the control, while no change of ACE2 or TMPRSS2 was observed." (PMID 34445093, 2021). "In HNECs treated with HMGB1 and OSM, upregulation of the COVID-19-related genes TMPRSS6, furin, and cathepsin L (CTSL) is observed." (PMID 34445093, 2021).